ERCC6L (ERCC excision repair 6 like, spindle assembly checkpoint helicase)
Diseases named in the same sentence as ERCC6L in open-access papers (continued):
Sharing a sentence is not in itself a finding about the gene and the disease.
cancer (continued). "Additional experiential evidence is needed to determine the effects of inhibiting ERCC6L on the progression of cancers of interest." (PMID 36550435, 2022). "Th2 cell infiltration positively correlated with ERCC6L expression levels across all studied cancer types." (PMID 36550435, 2022). "We found that ERCC6L expression was upregulated in patients from various cancer types than in normal tissue samples." (PMID 36550435, 2022). "The expression patterns of ERCC6L in normal and cancer patients at various clinical stages were explored based on TCGA datasets." (PMID 36550435, 2022). "Herein, we reported a comprehensive investigation of the tumor-promoting role of ERCC6L in various cancer types." (PMID 36550435, 2022). "We systematically studied the processes and pathways correlated with ERCC6L expression in nine cancers." (PMID 36550435, 2022). "A quantitative analysis of immune infiltration suggested a positive correlation between ERCC6L levels and the infiltration of Th2 immune cells in main cancer types." (PMID 36550435, 2022). "Excision repair cross-complementation group 6 like (ERCC6L), a polo-like kinase 1 (PLK1)-interacting checkpoint helicase, confers a high risk of cancer and enhances the progression of a variety of cancers." (PMID 36550435, 2022). "The present investigation aimed to elucidate the pan-cancer expression patterns of ERCC6L and to examine the possibility of using this gene for patient diagnosis and prognosis." (PMID 36550435, 2022). "To thoroughly understand the role of ERCC6L in cancer, we identified a set of its co-expressed genes and performed GO and KEGG analyses." (PMID 36550435, 2022). "Our analysis of immune cell infiltration in different cancer types demonstrated that Th2 cells were the most common class of infiltrating immune cells positively correlated with ERCC6L expression levels." (PMID 36550435, 2022). "To determine if ERCC6L is involved in immune cell infiltration, we quantified tumor purity in patients from each of the nine cancer categories." (PMID 36550435, 2022). "We systematically analyzed the expression levels of ERCC6L in a large panel of diverse cancer types and confirmed that ERCC6L was generally overexpressed in tumor tissues in most cases." (PMID 36550435, 2022). "We found that ERCC6L mRNA and protein expressions were evidently higher in cancer tissues compared with those in adjacent normal tissues in 45 pairs of cases." (PMID 34425559, 2021). "Remarkably, recent reports have identified ERCC6L as a critical mediator in the malignant biological behavior of various cancers." (PMID 34425559, 2021). "Excision Repair Cross-Complementation group 6-like (ERCC6L) has been shown to exhibit carcinogenic effect in several malignant tumors." (PMID 32891122, 2020). "ERCC6L is known to be an oncogenic protein of solid tumors, since the high expression leads to cancer cell proliferation and tumor growth." (PMID 32703154, 2020). "We analyzed a total of 4987 transcriptomes of 12 cancer types from The Cancer Genome Atlas (TCGA) and found that excision repair cross-complementation group 6-like (ERCC6L) was highly expressed in almost all cancer types." (PMID 28178669, 2017). "We analyzed 4987 transcriptome of 12 cancer types from The Cancer Genome Atlas (TCGA) and found that ERCC6L was consistently overexpressed in all of the 12 cancers compared to their corresponding normal controls (all p<0.001)." (PMID 28178669, 2017). "By analyzing 4987 cancer transcriptomes from The Cancer Genome Atlas (TCGA), we identified that excision repair cross-complementation group 6 like (ERCC6L), a newly discovered DNA helicase, is highly expressed in 12 solid cancers." (PMID 28178669, 2017). "Overall, the functional analysis indicated that esketamine suppressed ERCC6L, AHR and KIF2C may be the underlying mechanisms for its anti-cancer effects, although further study is needed." (PMID 37968758, 2023). "Most cancer types had higher ERCC6L mRNA levels than normal tissue." (PMID 36550435, 2022).
cancer (continued). "We began our study by examining the mRNA expression levels of ERCC6L in commonly diagnosed cancers." (PMID 36550435, 2022). "Then, we determined whether ERCC6L was also aberrantly expressed in various clinical stages of cancer and correlated with the survival of patients when classified into certain stages." (PMID 36550435, 2022). "Furthermore, KEGG analysis demonstrated that the cell cycle was the key process regulated by ERCC6L in cancer patients." (PMID 36550435, 2022). "Higher ERCC6L expression levels were correlated with poor prognosis for cancer patients." (PMID 36550435, 2022). "In particular, ERCC6L was the most significant prognostic gene whose expression level correlated with the overall survival (OS) of 15 different cancer types, suggesting that ATPCRs could be important prognostic factors." (PMID 35789070, 2022). "In addition, by integrating data from the Cancer Therapeutics Response Portal and the Genomics of Drug Sensitivity in Cancer project, we identified correlations between ERCC6L mRNA expression levels and sensitivity to cancer therapeutic drugs." (PMID 36550435, 2022). "We investigated whether ERCC6L could be used as a biomarker for the prognosis of cancer patients, given the pattern of ERCC6L upregulation in most cancers." (PMID 36550435, 2022). "ERCC6L protein was elevated in eight of nine cancers that we investigated." (PMID 36550435, 2022). "ERCC6L is a candidate biomarker for diagnosing and unfavorable prognosis of specific cancers." (PMID 36550435, 2022). "Importantly, we have analyzed the correlations between ERCC6L and tumor mutation burden (TMB), microsatellite instability (MSI) and neoantigens in these nine cancers." (PMID 36550435, 2022). "We then investigated ERCC6L genetic alterations in cancer patients." (PMID 36550435, 2022). "Deciphering the methods by which ERCC6L promoter activity is regulated may offer a greater understanding of the complexity of ERCC6L dysregulation in cancer." (PMID 36550435, 2022). "ERCC6L has been reported to act as a potential oncogenic protein in various cancers." (PMID 34425559, 2021). "Recently, ERCC6L also appears to play an important role in cancer progression." (PMID 34425559, 2021). "Taken together, our findings reveal that ERCC6L overexpression correlates with the development of the malignant tumor and may be an effectively prognostic factor and potential therapeutic target for HCC patients." (PMID 32891122, 2020). "In conclusion, our results suggest that ERCC6L may stimulates cancer cell proliferation by promoting cell cycle through a way of RAB31-MAPK-CDK2, and it could be a potential biomarker for cancer prognosis and target for cancer treatment." (PMID 28178669, 2017). "In conclusion, in this study, we report for the first time that ERCC6L may stimulates cancer cell proliferation and promotes tumor growth." (PMID 28178669, 2017). "Since ERCC6L knockdown can inhibit cancer cell proliferation in vitro and tumor growth in vivo, we wonder whether it was associated with clinical survivals." (PMID 28178669, 2017). "Furthermore, based on cancer tissue staining intensity, we categorized 85 patients with available clinical data into high ERCC6L (n = 61) and low ERCC6L (n = 24) groups, and subsequently conducted statistical comparisons of various clinicopathological features between the two groups." (PMID 40691138, 2025). "Additionally, we examined the ERCC6L protein levels in multiple common cancers." (PMID 36550435, 2022). "Moreover, ERCC6L has been depicted to exhibit oncogenic properties in colorectal, hepatocellular, and breast cancer cells, suggesting that it may be a viable target for cancer therapy." (PMID 36550435, 2022). "Moreover, identifying the DNA elements responsible for the demethylation of ERCC6L could lead to the development of novel therapeutic strategies for targeting ERCC6L in cancer." (PMID 36550435, 2022).
cancer (continued). "However, to obtain a complete picture of the genes or pathways affected by ERCC6L, it is necessary to perform the transcriptome profiling of cancer cells with dysregulated ERCC6L expression, and unbiased pathway enrichment analysis validate the bioinformatics results." (PMID 36550435, 2022). "Therefore, evidence from other models, such as mouse xenograft models with ERCC6L-depleted cancer cells and the subsequent flow cytometric analysis of immune cell percentages, can be utilized to elucidate better the correlations between ERCC6L expression levels and immune cell infiltration." (PMID 36550435, 2022). "Genes related to cancer stem cells and tumorigenesis, such as KPNA2, ECT2, ERCC6L and TUBB4B, and the cell-cycle regulators DLGAP5, KIF2C and BUB3 were also significantly upregulated in the CSPG+ group, and clustered well within the same area." (PMID 38251863, 2024). "Thus, as an effective biomarker, ERCC6L may serve as an adjuvant marker in combination with other prognostic markers or clinical parameters to aid in providing a more accurate patient prognosis with cancers subdivided into various pathological classes." (PMID 36550435, 2022). "The five genes (FANCB, KIF15, KIF4A, ERCC6L, and UBE2C) are all involved in fundamental cellular functions and found in many types of cancers." (PMID 32703154, 2020). "ERCC6L knockdown was demonstrated to result in downregulation of PLK1 which serves an important role in the control of the proliferation and cell cycle in cancer cells." (PMID 32703154, 2020). "To explore the mechanism of ERCC6L silencing in inhibiting cancer cell proliferation, we chose MCF-7 cell line to perform RNA-seq analysis after ERCC6L knockdown." (PMID 28178669, 2017). "Among 85 pairs of clinical samples, 61 out of 85 (71.8%) cancer tissues displayed increased ERCC6L expression compared to corresponding adjacent non-cancerous tissues." (PMID 40691138, 2025). "Furthermore, we investigated the impact of ERCC family genes on PFI and observed that only ERCC6L and ERCC8 maintained a significant correlation with expression levels, indicating their potent influence on cancer-related mortality." (PMID 39582530, 2024). "In this regard, MYC amplification and MYC overexpression do not drive ERCC6L dependence in a pan-cancer analysis of data from the DepMap portal (DepMap Public 23Q2+Score, Chronos)." (PMID 38253636, 2024). "Most of the tested cancer types did not significantly differ in ERCC6L expression levels with different groups of CNV; similarly, ERCC6L mRNA expression levels did not significantly correlate with ERCC6L CNVs." (PMID 36550435, 2022). "We have shown negative correlations between ERCC6L mRNA expression levels and its promoter methylation in most cancers, excluding PAAD." (PMID 36550435, 2022). "Besides, their further studies considered that ERCC6L might affect the cell cycle via RAB31-MAPF-CDK, so as to promote cancer cell proliferation." (PMID 30555514, 2018). "Most cancer types, excluding PAAD, exhibited a negative correlation between ERCC6L mRNA expression levels and promoter methylation." (PMID 36550435, 2022).
tumor (24 papers, 2012 to 2025). "We found that ERCC6L was upregulated in GC tissues, and its expression was associated with tumor size, clinical stage, and poor prognosis in GC patients." (PMID 34425559, 2021). "This study demonstrated that the ERCC6L expression was upregulated in HCC tumor tissue, which exhibited closely associated with tumor progression and poor prognosis." (PMID 32891122, 2020). "Meanwhile, ERCC6L expression levels were positively associated with clinicopathological characteristics, including Edmondson stage, tumor encapsulation, and female gender." (PMID 32891122, 2020). "Additionally, we also revealed the potential relationship between KIF4A and ERCC6L, that is, there was a direct interaction between KIF4A and ERCC6L, and both are closely associated with mitosis and contribute to tumor growth and metastasis." (PMID 37667329, 2023). "Moreover, ERCC6L expression levels were higher in patients with higher clinical tumor grades and were associated with poor prognoses at these stages." (PMID 36550435, 2022). "Functionally, ERCC6L promoted LUAD cell stem-like characteristics by regulating tumor glycolysis via the VHL/HIF-1α pathways." (PMID 40691138, 2025). "After 30 days, tumors were harvested, and their volume and weight were measured, showing significant suppression of tumor growth upon ERCC6L knockdown." (PMID 40691138, 2025). "Multivariate analysis confirmed that low ERCC6L expression was an independent predictor for reduced tumour-free survival of LUAD patients." (PMID 40691138, 2025). "Conversely, ERCC4 and ERCC6L2 displayed distinct correlation patterns compared to ERCC6L and the other three genes, suggesting their tumor-suppressing function." (PMID 39582530, 2024). "ERCC6L knockdown was first found to significantly suppress the number and area of lung metastases in tumor-bearing mice." (PMID 37667329, 2023). "Statistics showed that ERCC6L was highly expressed in 52.8% of tumor tissues, while all normal tissues were low ERCC6L expression (P < 0.001)." (PMID 36726012, 2023). "The tumor growth rate of different genotypes of tumor-bearing mice was monitored to determine the effect of ERCC6L on tumor development." (PMID 37667329, 2023). "The fluorescence intensity of tumor was ERCC6L group, ERCC6L + shKIF4A group and shKIF4A group in order from high to bottom." (PMID 36726012, 2023). "Compared with that in the nude mice inoculated with control cells, tumor growth in nude mice inoculated with ERCC6L-knockdown 231 cells was significantly inhibited." (PMID 37667329, 2023). "We also measured the expression level of kinesin family member 4 (KIF4A) in tumor tissues, which also plays a role in chromosome disjunction during mitosis, and found that KIF4A was highly expressed in tumor tissues with high ERCC6L expression levels." (PMID 37667329, 2023). "Unreasonably, ERCC6L was upregulated in tumor samples, but its expression predicted a better prognosis in the univariate and multivariate Cox regression analyses, so it was excluded from further study." (PMID 36159981, 2022). "Taking the in vitro and in vivo results together, it was shown that Txnip, Aox1, Per3 and Ypel3 were consistently upregulated in both tumor lines and Acat2, Clspn and Ercc6l were downregulated." (PMID 33407762, 2021). "To further determine the role of ERCC6L in tumor growth, we established xenograft tumor mouse model." (PMID 32891122, 2020). "Knockdown of ERCC6L expression significantly inhibited proliferation, invasion and metastasis in vitro and tumor growth in vivo, and it promoted cell cycle arrest and apoptosis." (PMID 32891122, 2020). "High ERCC6L expression was also found in the patients with non-tumor encapsulation or III-IV pathological stage, which often indicating highly invasive, metastatic, and poor prognosis." (PMID 32891122, 2020).
tumor (continued). "In the present study, we clarified that expression of FANCB, KIF15, KIF4A, ERCC6L, and UBE2C are regulated by DNA methylation changes of their promoter CpGis and closely associated with tumor prognosis in HCC using the TCGA database." (PMID 32703154, 2020). "Univariate analysis showed that ERCC6L, tumor size and pathological stage were correlated with OS in HCC patients." (PMID 32891122, 2020). "ERCC6L was highly expressed in HCC tissue compared with tumor adjacent tissues in 90 paired samples." (PMID 32891122, 2020). "The xenograft experiment showed that silencing of ERCC6L strikingly inhibited tumor growth from the 7th day after xenograft in nude mice." (PMID 28178669, 2017). "To date, the precise mechanism by which ERCC6L regulates tumor cell development and progression in LUAD remains unclear." (PMID 40691138, 2025). "Consequently, we evaluated HIF-1α‘s contribution to ERCC6L-regulated tumor growth by genetically knocking down HIF-1α in A549 xenografts." (PMID 40691138, 2025). "In this study, ERCC6L was found to be highly expressed in BC patients, and its expression level was positively correlated with the malignant grade of the tumor and the poor prognosis of patients, which to some extent suggested that ERCC6L played an essential role in the malignant progression of BC." (PMID 37667329, 2023). "In addition, ERCC6L deletion mice had a lower tumor burden and individual tumor weight than ERCC6L+/+ PyMT mice, with significant statistical discrepancies." (PMID 37667329, 2023). "Ten pairs of tumor tissue samples and adjacent normal breast tissues from BC patients were used to assess the expression of ERCC6L by Western blotting, and the results showed that ERCC6L was more highly expressed in BC tissues than in normal controls." (PMID 37667329, 2023). "However, the exact mechanism by which ERCC6L regulated tumor cell development and progression in LSCC remained unclear." (PMID 36726012, 2023). "Knocking down ERCC6L significantly inhibited tumor growth in nude mice." (PMID 37667329, 2023). "Furthermore, the ERCC6L expression level was markedly higher in tumor samples with higher clinical grades." (PMID 36550435, 2022). "With the exception of TOP2A and ERCC6L, which were upregulated in tumor samples." (PMID 36067196, 2022). "In this study, we found that higher ERCC6L expression levels are detected in tumor tissues than in adjacent normal tissues, suggesting that ERCC6L may play a crucial role in the progression of HCC." (PMID 32891122, 2020). "ERCC6L expression positively correlated with gender, tumor encapsulation, and pathological stage." (PMID 32891122, 2020). "Increasing evidences have demonstrated that ERCC6L is an important oncogene in tumor progression." (PMID 32891122, 2020). "In addition, a multivariate analysis demonstrated that the ERCC6L (HR 0.437, p = 0.045), the tumor size (HR 0.449, p = 0.037) and gender (HR 2.970, p = 0.026) were independent prognostic indicators for HCC patients." (PMID 32891122, 2020). "In addition, we assessed the function of ERCC6L in tumor cell proliferation, apoptosis, migration, and molecular mechanisms in vitro and in vivo." (PMID 32891122, 2020). "The high expression of ERCC6L and MYB may be associated with the improvement of patients’ survival, suggesting that ERCC6L and MYB may play a potential protective role by inhibiting tumor progression or enhancing treatment sensitivity." (PMID 40672391, 2025). "Furthermore, ERCC6L promotes tumor progression via the PI3K/AKT and NF-κB pathway in HCC." (PMID 34425559, 2021). "Moreover, the tumor weight in the shERCC6L group was significantly decreased than that in NC group (p < 0.05), showing that knockdown ERCC6L expression could retard HCC growth in vivo." (PMID 32891122, 2020). "Overall, ERCC6L and MYB have significant biological and clinical roles in various tumors, but their expression and prognostic value differ by tumor type." (PMID 40672391, 2025).